Y_RNA (Y RNA )
Gene: Miscellaneous RNA gene on chromosome 17 (48,479,097 to 48,479,198, forward strand). Ensembl gene ENSG00000206805.
Homologues: Orthologues: chimpanzee Y_RNA (100% identical), macaque Y_RNA (91% identical). Paralogues in human: RNY3 (95% identical), Y_RNA (94% identical), Y_RNA (93% identical), RNY3P1 (92% identical), Y_RNA (92% identical), RNY3P14 (91% identical), Y_RNA (91% identical), RNY3P16 (90% identical), Y_RNA (90% identical), Y_RNA (89% identical), RNY3P4 (88% identical), RNY3P9 (88% identical), and 99 more.